ATM (ATM serine/threonine kinase)
Diseases named in the same sentence as ATM in open-access papers (continued):
Sharing a sentence is not in itself a finding about the gene and the disease.
Hodgkins lymphoma (4 papers, 2004 to 2024). A heterogeneous group of malignant lymphoid neoplasms of B-cell origin characterized histologically by the presence of Hodgkin and Reed-Sternberg (HRS) cells in the vast majority of cases. "Some lymphoid malignancies, such as mantle cell lymphoma, diffuse large B-cell lymphomas, and Hodgkin lymphomas, are also associated with acquired ATM mutations." (PMID 30662441, 2018). "ALL and Hodgkin lymphoma share susceptibility to ATM and NBN mutations." (PMID 34117277, 2021). "Missense variants of the ATM gene are a rare event in childhood Hodgkin disease." (PMID 14735203, 2004). "LMP1 upregulate BMI-1 in Hodgkin's lymphomas, a Polycomb related protein, and both proteins combine their effects to downregulate ATM expression." (PMID 30662441, 2018). "The aim of this study was to investigate the possible involvement of the ATM gene in the carcinogenesis of Hodgkin disease in children." (PMID 14735203, 2004). "The aim of the study was to investigate the possible involvement of ATM gene in the pathogenesis of Hodgkin lymphoma in children." (PMID 14735203, 2004). "Our results indicate that missense variants of the ATM gene occur in Hodgkin's disease in children (9%), but at a low frequency, and thus do not play a major role in the oncogenesis of the disease in our childhood population in Israel." (PMID 14735203, 2004). "Thus, LOH of the ATM gene is rarely involved in childhood Hodgkin disease." (PMID 14735203, 2004). "Moreover, no truncating germ-line ATM mutations were detected in 52 survivors of Hodgkin's disease, adults and children, who developed secondary neoplasms." (PMID 14735203, 2004).
Hypertension (4 papers, 2017 to 2025). The presence of chronic increased pressure in the systemic arterial system. "The most connected genes (hub genes) for the interaction network were lysine methyltransferase 2A (KMT2A) for incident hypertension, ataxia-telangiectasia mutated (ATM) for systolic BP, and beta-actin (ACTB) for diastolic BP." (PMID 39972178, 2025). "Of specific genes, lysine methyltransferase 2 A (KMT2A) was found to be central for incident hypertension, ataxia-telangiectasia mutated (ATM) for systolic blood pressure, and beta-actin (ACTB) for diastolic blood pressure." (PMID 39972178, 2025). "Upon phosphorylation and activation of NF-κB by ATM, eNOS activity is reduced leading to low levels of NO inducing vasoconstriction, oxidative stress, and inflammation which can lead to hypertension." (PMID 39972178, 2025). "This study offers new perspectives on immune modulation from exercise in hypertension, enhancing existing knowledge of ATM diversity and adipose-vascular interactions." (PMID 41516126, 2025). "By contextualizing these findings within a contemporary perspective on ATM variability, our research enhances the increasing recognition of adipose–immune–vascular interactions in hypertension." (PMID 41516126, 2025). "Lastly, to the best of our knowledge none of the previous EWAS or TWAS published on hypertension related phenotypes have reported KMT2A, ATM, and ACTB among their top findings." (PMID 39972178, 2025).
hypertrophy (4 papers, 2017 to 2025). Hypertrophy is the increase in the volume of an organ or tissue due to the enlargement of its component cells. "Previously, we provided evidence that Western‐type diet in male ATM deficient mice accelerates body weight gain, induces systolic dysfunction with increased preload, and exacerbates cardiac hypertrophy, apoptosis, and inflammation." (PMID 36117462, 2022). "The preservation of heart function in ATM‐deficient females post‐WD may involve decreased myocyte apoptosis and increased myocardial hypertrophy." (PMID 36117462, 2022). "For SNP rs189037 in ATM gene, heterozygous mutation might result in LV concentric development, whereas homozygous mutation might further induce LV eccentric hypertrophy." (PMID 34124196, 2021).
kidney clear cell carcinomas (4 papers, 2018 to 2023). "Ten pathogenic or likely pathogenic (P/LP) variants were identified in 11 sporadic clear cell renal cell carcinoma patients (10.38%), including rarely reported ATM (n=1), MUTYH (n=1), NBN (n=1), RAD51D (n=1), and BRCA2 (n=1)." (PMID 33062672, 2020). "Other variants (BRCA2 (c.5900A>G; p.(Lys1967Arg)), ATM (c.1810C>T; p.(Pro604Ser)) and MET (c.2962C>T; p.(Arg988Cys)) were found in non-syndromic patients (3/74; 4%) with clear cell renal cancer before 50 years of age." (PMID 38002934, 2023).
lymphopenia (4 papers, 2016 to 2022). Reduction in the number of lymphocytes. "This condition phenocopies Gsnor−/− mice lymphopenia and is in line with results obtained in Jurkat and CD4+ T cells, in which pharmacological inhibition of ATM is associated with cell death and reduction of proliferation upon stimulation." (PMID 33245190, 2021).
lymphoproliferative disorders (4 papers, 2016 to 2025). "Loss of heterozygosity happens frequently in sporadic tumors of lymphoid origin, and a high prevalence of ATM gene alterations in diverse sporadic lymphoproliferative disorders has been reported." (PMID 34267759, 2021).
metastatic cancer (4 papers, 2015 to 2023). A carcinoma which has spread from the original site of growth to another anatomic site. "Enrolling patients with tumors harboring pathogenic mutation genes other than ATM, BRCA1 and BRCA2 was challenging owing to the low prevalence of pathogenic alterations affecting these genes in patients with metastatic cancer (<1%)." (PMID 37277454, 2023). "AZD0156 is a first-in-class orally available ATM inhibitor and is the only ATM inhibitor enrolled in clinical trials (phase I, in combination with olaparib for locally advanced/metastatic cancer, NCT02588105)." (PMID 29757235, 2018). "ATM depletion in metastatic cancer cells reduced cell migration and invasion." (PMID 26030852, 2015).
oral squamous cell carcinoma (4 papers, 2011 to 2025). "Our aim was to analyze ATM and APC methylation and its relationship with oral squamous cell carcinoma (OSCC)." (PMID 22414247, 2011).
Parkinson disease (4 papers, 2016 to 2025). A progressive degenerative disorder of the central nervous system characterized by loss of dopamine producing neurons in the substantia nigra and the presence of Lewy bodies in the substantia nigra and locus coeruleus. "Also of interest is the finding that the loss of ATM function does not correlate with the degree of α-synuclein involvement, a neuropathology most commonly associated with Parkinson’s disease, but often found in AD brains as well." (PMID 27022623, 2016).
radiation pneumonitis (4 papers, 2016 to 2023). Inflammation of the lung due to harmful effects of ionizing or non-ionizing radiation. "Some independent studies have shown the ATM (rs189037 (G>A)) A allele as a risk allele for radiation pneumonitis in NSCLC patients upon radiotherapy." (PMID 27258253, 2016). "Furthermore, certain ATM (ataxia telangiectasia mutated) gene polymorphisms have been associated with increased risk of radiation pneumonitis." (PMID 33521012, 2020). "In addition, haplotype analysis showed that patients carrying ATM rs228590 TT/CT or rs189037 AG/GG genotypes or rs228590T/rs189037G/rs1801516G (G-T-G) haplotypes had a lower risk of severe radiation pneumonitis when receiving definitive radio(chemo)therapy." (PMID 27258253, 2016).
Rett syndrome (4 papers, 2013 to 2025). A severe neurodevelopmental disorder affecting the central nervous system. "We previously observed normal DSB repair rates in other human syndromes with disordered HC (e.g. Rett Syndrome), but such cells display a diminished requirement for ATM for HC-DSB repair." (PMID 23969417, 2013).
Sepsis (4 papers, 2021 to 2023). Sepsis is defined as life-threatening organ dysfunction caused by a dysregulated host response to infection. "The results indicated that 8 genes (MAPK14, MAPK8, TLR4, MAP3K5, CYBB, DUSP1, MAPK1 and ATM) might be closely related to the occurrence of sepsis." (PMID 36117534, 2022). "Because Epi is protective in sepsis through ATM-mediated signaling, and due to the genotoxicity of this class of drugs, we asked whether cytokine regulation by anthracyclines depended on the induction of DDRs." (PMID 36476511, 2022). "Activation of this TF, that is tightly associated with epigenetic change, could be one mechanistic pathway through which ATM modulates epigenetic reprograming of innate immune cells and HSCs during sepsis." (PMID 34356379, 2021). "Known connections between ATM regulation of the key transcription factor involved in regulating most of the genes that become tolerized in suppressed innate immune cells of sepsis survivors further raises the possibility that ATM is involved in this epigenetic reprogramming." (PMID 34356379, 2021). "Moreover, increased ATM activation through oxidation may lead to increased autophagy and better sepsis outcomes." (PMID 34356379, 2021). "Microarray analysis has indicated abnormalities in the expression of immune-related genes in children with sepsis, including FYN, FBL, ATM, WDR75, FOXO1, and ITK." (PMID 36855207, 2023).
thyroid (4 papers, 2015 to 2024). "Although the results are inconclusive, we speculated an association between thyroid disorders and ATM and γH2AX expression." (PMID 25861265, 2015). "These analyses revealed that the most affected cellular processes are the VEGFA−VEGFR2 and PDGF signaling pathways, the ATM-dependent DNA damage response, and the PI3K−AKT−mTOR signaling pathway, all of which are known to be involved in thyroid tumorigenesis." (PMID 35625697, 2022).
angiosarcoma (3 papers, 2023 to 2025). A malignant tumor arising from the endothelial cells of the blood vessels. "In the COSMIC database, somatic ATM variants are reported in 8% (82/1077) of soft tissue tumors, of which 16 are angiosarcomas." (PMID 39594770, 2024). "The detection of the biallelic loss of ATM in an angiosarcoma tumor in our study contributes to the growing knowledge about ATM in tumorigenesis." (PMID 39594770, 2024). "Also, in the case of a doxorubicin-resistant canine hemangiosarcoma cell line established to study drug resistance, it was found that the DDR pathway was attenuated, as the mRNAs for ATM, ATR, and Chk1 were significantly decreased, suggesting a possible role for ATR in doxorubicin resistance." (PMID 37655260, 2023).
bladder tumors (3 papers, 2020 to 2024). "Of note, ATM gene mutations increased response to immunotherapy in bladder tumors by affecting the tumor microenvironment." (PMID 33266377, 2020). "RT-associated bladder tumors were significantly enriched for alterations in KDM6A and ATM, whereas CTRL tumors were enriched for CDKN2A mutation." (PMID 39113632, 2024). "Mutations in ATM, RB1, and FANCC genes occur in approximately 11%, 14%, and 2% of bladder tumors, respectively." (PMID 33266377, 2020).
bladder urothelial cancer (3 papers, 2021 to 2022).
childhood cancer (3 papers, 2020 to 2022).
cognitive decline (3 papers, 2016 to 2020). "Given that filamentous actin has been suggested to be selectively lost from synapses during the early stages of AD33, DBN and ATM may regulate actin organization in concert, and thereby safeguard against early synaptic dysfunction and cognitive decline." (PMID 30700723, 2019). "Unlike AD, where clinically significant cognitive decline does not typically occur before age 65, A-T symptoms appear in early childhood and are caused exclusively by mutations in the ATM (A-T mutated) gene." (PMID 27538496, 2016). "Together, these findings highlight how DDR, and in particular ATM protein, plays a fundamental role in cognitive decline not only in A-T, opening the way to new possible pharmacological targets for cognitive impairments." (PMID 32858941, 2020). "Moreover, failure in ATM signalling and the consequent reduction of DDR efficiency in both the AD mouse model and human AD tissues suggest that altered DDR could be an important contributor not only to neurodegeneration in AD, but also to cognitive decline." (PMID 32858941, 2020).
Cognitive impairment (3 papers, 2013 to 2023). Abnormal cognition is characterized by deficits in thinking, reasoning, or remembering. "AT patients show variable phenotypes ranging from neurologic abnormalities and cognitive impairments to more recently described neuropsychiatric features pointing to symptoms hardly ascribable to the canonical functions of ATM in DNA damage response (DDR)." (PMID 37681912, 2023). "Thus, this study provides a rationale for the cognitive defects described in A-T and links ATM among those proteins possibly involved in neuropsychiatric disorders characterized by altered E/I balance and inhibitory system." (PMID 32858941, 2020). "These increases paralleled increased phosphorylation of several ATM-specific substrates detected in the same regions from the corresponding cases suggesting ample ATM activation in brain regions vulnerable to neurodegeneration in AD and in mild cognitive impairment." (PMID 23861893, 2013).
colon adenoma (3 papers, 2017 to 2019). An adenoma that arises from the colon. "Since the loss of ATM expression is associated with worse prognosis in CRC patients and ATM expression is reduced in colonic adenomas, further repression by combined E2 and low oxygen tension may enhance tumorigenesis." (PMID 29137421, 2017).
colorectal adenocarcinoma (3 papers, 2019 to 2023). The most common type of colorectal carcinoma. "All six patients had at least one 1st or 2nd-degree relative with ATM-associated cancer including breast, pancreatic, prostate, gastric, and colorectal adenocarcinomas." (PMID 36865800, 2023).
cystic kidney disease (3 papers, 2021 to 2024). A congenital or acquired kidney disorder characterized by the presence of renal cysts. "Taken together, these results, suggest that the ATM-DDR pathway is dispensable for the progression of cystic kidney disease in ADPKD." (PMID 33802342, 2021). "Therefore, in this study, we hypothesized that reducing either ATM or ATR attenuates cystic kidney disease." (PMID 33802342, 2021). "Insights from an animal model featuring altered loci for both PKD1 and ATM (Pkd1RC/RC/Atm+/− or Pkd1RC/RC/Atm−/−) revealed no discernible alteration in the progression of cystic kidney disease, even at the age of 6 months." (PMID 38474184, 2024). "Furthermore, pharmacological inhibition of ATM using AZD0156 reduced γH2AX foci and exacerbated cystic kidney disease." (PMID 36293397, 2022). "Finally, combined low-dose cisplatin with AZD0156 (an ATM inhibitor) non-selectively reduced γH2AX in both cystic and non-cystic tubular cells and exacerbated cystic kidney disease." (PMID 36293397, 2022). "Lastly, and unexpectedly, the chronic progression of cystic kidney disease in vivo was not altered by genetic ablation of ATM from birth, in either Pkd1RC/RC/Atm+/− or Pkd1RC/RC/Atm−/− mice." (PMID 33802342, 2021). "However, the progression of cystic kidney disease in Pkd1RC/RC mice was not altered by genetic ablation of ATM from birth, in either heterozygous (Pkd1RC/RC/Atm+/−) or homozygous (Pkd1RC/RC/Atm−/−) mutant mice at 3 months." (PMID 33802342, 2021).
dermatitis (3 papers, 2019 to 2024). An inflammatory process affecting the skin. "The group of rare monoallelic ATM PV carriers was composed of three patients, of which two experienced grade 1 dermatitis and one woman experienced grade 2." (PMID 38611095, 2024). "In this prospective cohort study, we found that symptoms of dermatitis radiation, pain, pruritus and fatigue were associated with the expression level of some genes of the DNA-damage response pathway (FDXR, SESN1, XPC, ZMAT3, ATM, BCL2/BAX, and CDKN1A)." (PMID 31632918, 2019). "While the expression level of FDXR gene increased in patients experiencing a high grade of dermatitis radiation, those of SESN1, ATM, XPC, ZMAT3, CDKN1A genes decreased when radiation toxicity was manifested." (PMID 31632918, 2019).
endothelial dysfunction (3 papers, 2013 to 2024). In vascular diseases, endothelial dysfunction is a systemic pathological state of the endothelium (the inner lining of blood vessels) and can be broadly defined as an imbalance between vasodilating and vasoconstricting substances produced by (or acting on) the endothelium. "The study reveals that individuals with homozygous ATM gene mutations, affected by AT, and their parents, who carry heterozygous ATM mutations, show endothelial dysfunction, increased NOX2 activation and impaired antioxidant activity (Central illustration)." (PMID 39326070, 2024). "This study demonstrates that individuals with ATM mutations experience endothelial dysfunction, increased oxidative stress, and elevated thrombus formation." (PMID 39326070, 2024). "In conclusion, this study sheds light on the intricate relationship among endothelial dysfunction, oxidative stress, and individuals carrying mutations in the ATM gene." (PMID 39326070, 2024). "The knockout of ATM could attenuate endothelial dysfunction and cell senescence in the aorta of diabetic mice." (PMID 38027164, 2023).
epilepsy (3 papers, 2015 to 2025). A brain disorder characterized by episodes of abnormally increased neuronal discharge resulting in transient episodes of sensory or motor neurological dysfunction, or psychic dysfunction. "Within the network, many genes are related to inflammation and apoptosis, such as MAPK1, ATM, MYD88, RBL1, TRAF6, PIK3CD, IFNAR2, etc, indicating that these miRNAs may play a role in drug-resistant epilepsy through inflammation and apoptosis." (PMID 25984652, 2015).
familial melanoma (3 papers, 2021 to 2025). Familial melanoma (FM) is a rare inherited form of melanoma characterized by development of histologically confirmed melanoma in two first degrees relatives or more relatives in an affected family. "While PVs have also been detected in several other genes, including CDK4, BAP1, ATM, MITF and multiple telomere stability genes TERT, POT1, ACD, and TERF21P, about half of the cases of familial melanoma remain unexplained." (PMID 40072281, 2025).
Hepatic steatosis (3 papers, 2021 to 2023). Steatosis is a term used to denote lipid accumulation within hepatocytes. "Another tumor suppressor, regulator of G protein signaling 6 (RGS6), is upregulated in the liver of NAFLD patients, forms a complex with ATM in the liver, promotes ATM phosphorylation, and drives hepatic steatosis." (PMID 37033223, 2023). "A recent study that analyzed the expression of messenger RNAs, total proteins, or phosphoproteins related to the ATM pathway of individuals with healthy liver, hepatic steatosis, and NASH, found a causal association between the ATM pathway and NAFLD." (PMID 37147676, 2023). "MAPK8-associated diseases include fatty liver disease and hepatitis C. The pathways related to MAPK8 include the ATM (serine/threonine kinase) pathway and the link between physicochemical characteristics and toxicity-related pathways." (PMID 34335821, 2021).